NCOA3 (nuclear receptor coactivator 3)
Diseases named in the same sentence as NCOA3 in open-access papers (continued):
Sharing a sentence is not in itself a finding about the gene and the disease.
breast carcinoma (continued). "Furthermore, we validated that both miR-17 and miR-20b directly targeted and inhibited the expression of NCOA3 and therefore reduced taxol-induced cytotoxicity in breast cancer cells." (PMID 27831559, 2016). "Furthermore, by luciferase reporter assays, we further validated that both miR-17 and miR-20b directly binded the 3′-untranslated region of NCOA3 mRNA and inhibited its expression in breast cancer cells." (PMID 27831559, 2016). "In addition, we also detected the mRNA levels of NCOA3 in the adjacent normal tissues of above breast cancer tissues." (PMID 27831559, 2016). "We showed NCOA3 decreased breast cancer cell apoptosis induced by taxol." (PMID 27831559, 2016). "Moreover, overexpression of NCOA3 enhanced breast cancer cell resistance to taxol, whereas depletion of NCOA3 decreased taxol resistance." (PMID 27831559, 2016). "Our study suggested miR-17, miR-20b and NCOA3 may serve as some predictive biomarkers and potential therapeutic targets in taxol-resistant breast cancer treatment." (PMID 27831559, 2016). "Finally, we also measured VEGFa mRNA expressed in the mammary tumors with knockout of Ncoa3, another member of the SRC family." (PMID 26287601, 2015). "Moreover, we observed a significant correlation of PLAC1 expression and NCOA3 overexpression in a cohort of ERα-positive breast cancer patients." (PMID 24304549, 2013). "Moreover, significant higher transcript levels of PLAC1 were found only in ERα-positive human breast cancer samples which also show a NCOA3 overexpression." (PMID 24304549, 2013). "Thus our data introduce PLAC1 as a possible downstream effector of NCOA3 mediated actions in ERα-positive breast cancer cells." (PMID 24304549, 2013). "Moreover, we demonstrate a relevant correlation of PLAC1 expression and NCOA3 overexpression in human breast cancer tissues restricted to the ERα-positive samples." (PMID 24304549, 2013). "Therefore, we subdivided the 48 breast cancer samples into two groups depending on NCOA3 expression levels." (PMID 24304549, 2013). "Silencing of NCOA3 results in loss of PLAC1 transactivation after E2-stimulation only in ERα-positive MCF-7 but not in ERα-negative SK-BR-3 breast cancer cells." (PMID 24304549, 2013). "However, genes of hot regions are linked to breast cancer disease such as BACH1, RAD51C, CYP24A1 and NCOA3." (PMID 23368971, 2013). "Because of the critical importance of coregulators for ERα function, we hypothesized that breast cancer risk is influenced by SNPs within the coactivators SRC-1/NCoA1 and SRC-3/NCoA3/AIB1 and the corepressors NCoR and SMRT/NCoR2." (PMID 20003447, 2009). "Thus, we set out to identify novel single nucleotide polymorphisms (SNPs) within SRC-1 (NCoA1), SRC-3 (NCoA3, AIB1), NCoR (NCoR1), and SMRT (NCoR2), and test the most promising SNPs for associations with breast cancer risk." (PMID 20003447, 2009). "Genes such as NCOA3, PPM1D, PSMD6 and BCAS2 were detected with high expression and copy numbers in MCF-7 cells, and these genes have been associated with breast cancer progression." (PMID 18350142, 2008). "Length of repeat variations in the androgen receptor gene and in the steroid nuclear receptor coactivator AIB1/NCOA3 were reported to affect breast cancer risk, but this has not been confirmed." (PMID 17213823, 2007). "Therefore, this inverse correlation between NCOA3 and miR-17/miR-20b expression may be responsible for taxane resistance in breast cancer." (PMID 33182737, 2020). "Further inspection of the modules found that three of these modules are related to known breast cancer related processes such as epithelium development, chromosome organization, and mitotic cell cycle including well-known breast cancers genes such as NCOA3, AURKA, MKI67, and FOXA1." (PMID 30906311, 2019). "The breast cancer, gastric cancer, and nonsmall cell lung cancer patients with high expression of NCOA3 have significantly shorter overall survival times, indicating that NCOA3 may be an indicator of poor prognosis." (PMID 29360267, 2018).
breast carcinoma (continued). "In addition, we detected the expression of NCOA3 in several breast cancer cells lines." (PMID 27831559, 2016). "Subsequently, we investigated whether NCOA3 expression was regulated by miRNAs in breast cancer." (PMID 27831559, 2016). "Therefore, we investigated the relationship between NCOA3 with taxol resistance of breast cancer." (PMID 27831559, 2016). "Since we detect a significant correlation between NCOA3 overexpression and PLAC1 expression in ERα-positive breast cancer patients this adds to the relevance of understanding the role of PLAC1 in the NCOA3/ERα-signaling pathway and might open new therapeutic concepts for breast cancer." (PMID 24304549, 2013). "However, ETS-2 has also been implicated in prostate cancer and together with other factors including ETS-1, SRC-1 (v-src avian sarcoma [Schmidt-Ruppin A-2] viral oncogene homolog), AIB-1 (nuclear receptor coactivator 3) and NcoR (nuclear receptor co-repressor), breast cancer." (PMID 18958307, 2008). "In luminal breast cancer cells, FOXF2 initiates the recruitment of NCoA3, forming a complex that attaches to the WNT2B and FZD1 promoters." (PMID 40003882, 2025). "BET inhibitors are commonly used chemotherapy drugs in breast cancer treatment, and NR5A2 and NCOA3 mainly mediate their resistance." (PMID 39664391, 2024). "The recruitment of CARM1 to the ERα target promoters is dependent on nuclear receptor coactivator 3 (NCOA3; also known as steroid receptor coactivator-3, SRC-3), which is overexpressed in aggressive breast cancers together with CARM139." (PMID 36639369, 2023). "Zhou's study shows that NCOA3 can interact with E2F1 to promote the proliferation of hormone-dependent and independent breast cancer cells." (PMID 35898549, 2022). "The large majority (10/13) of these genes were reported to play a role in the regulation of estrogen and/or progesterone response in human breast cancer (NCOA7:; NCOA3:; USP22:; MED24:; CCAR1:; CRY2:; STAT5B:; PAGR1:; TAF1:; PHB2:)." (PMID 35996163, 2022). "PFKFB4 is reported to be a robust stimulator to nuclear receptor coactivator 3 (NCOA3) which drives glucose flux towards the PPP and up-regulates the activity of estrogen receptor to further promote aggressiveness of breast cancer." (PMID 34593007, 2021). "Dysregulation of ER coregulators such as Amplified-in-breast cancer 1 (AIB1/NCOA3) and steroid receptor coactivator-1 (SRC-1) in breast cancer promotes invasion and metastasis." (PMID 32824207, 2020). "While the functions of NCOA1 and NCOA3 have been widely explored in breast cancer, little is known about the biological roles of NCOA2 in regulating genes involved in breast cancer progression." (PMID 30941313, 2019). "Further, XBP1 upregulation promotes the expression of nuclear receptor coactivator 3 (NCOA3) and induces resistance of luminal type of breast cancers to anti-hormonal agents." (PMID 31739582, 2019). "Nuclear receptor coactivator 3 (NCOA3), also known as AIB1, SRC-3, or TRAM-1, was cloned as a gene which was amplified in breast cancer." (PMID 30791431, 2019). "The most widely studied steroid receptor coactivator family in breast cancer are the p160 kDa group of SRC −1 (NCOA1), −2(NCOA2), and −3 (NCOA3/AIB1)." (PMID 30416486, 2018). "We have recently shown that expression of NCOA3 is regulated by XBP1 during the conditions of UPR, as well as estrogen stimulation in human breast cancer cells." (PMID 29545931, 2018). "Transcript expression of NCOA3 and PLAC1 in 48 human breast cancer samples was examined by qRT-PCR and statistical analysis was performed using Student’s t-test." (PMID 24304549, 2013). "Recent data from breast cancer cell lines shows that miR-17-5p of the miR17-92 cluster down regulates the proto-oncogenic transcriptional activator AIB1 (amplified in breast cancer 1), also known as SRC-3, TRAM1, NCOA3 and RAC3." (PMID 21532838, 2010).
breast carcinoma (continued). "The breast cancer oncogene/coactivator AIB1/SRC-3/NCOA3 is regulated by mir-17-5p and there is a reciprocal relationship between reduced miR-17-5p and increased AIB1 in breast cancer cells." (PMID 19881910, 2009). "NCOA3 is the p160 ESR1 transcriptional coactivator and is amplified or overexpressed in breast cancer." (PMID 19007432, 2008). "Therefore, in luminal breast cancer and basal-like breast cancer cells, FOXF2 differentially modulates the transcription of WNT2B and FZD1 by enlisting NCoA3 and NCoR1, respectively." (PMID 40003882, 2025). "PFKFB4 was reported to phosphorylate SRC-3 (NCOA3) at Ser857 in breast cancer with no other report on its potential substrate." (PMID 34593007, 2021). "This locus contains 24 protein-coding genes, among which at least 10 (e.g. NCOA3, SNAI1/Snail1, CEBPB and PTPN1) are involved in mammary gland development, ERα-related regulation, or breast cancer, suggesting an importance of this locus for mammary gland morphogenesis." (PMID 31642473, 2019). "In addition, NCOA3 (AIB1), a member of the NCoA HAT family, was reported to be highly expressed in breast cancer cells, and in certain leukemias." (PMID 30558227, 2018). "In addition, we verified that NCOA3 was also upregulated in taxol-resistant MCF-7 and 231 breast cancer cells relative to their parental cells." (PMID 27831559, 2016). "In addition, forced expression of NCOA3 observably enhanced Bcl-2 and phosphated AKT expression in the two breast cancer cells." (PMID 27831559, 2016). "On the other hand, CD31 expression showed no significant changes in the mammary tumors (n = 5) of Ncoa3−/− × Tg(MMTV-PyMT) mice when compared with the mammary tumors (n = 5) of Tg(MMTV-PyMT) mice (data not shown)." (PMID 26287601, 2015). "Noteworthy, silencing of NCOA3 in MCF-7 cells did not result in complete loss of PLAC1 expression, as basal expression of PLAC1 in breast cancer is not dependent on ERα-signaling but rather on the presence of SP1 and C/EBPβ-2." (PMID 24304549, 2013). "Our findings provide the basis to further dissect the role of PLAC1 in the ERα-signaling pathway in breast cancer and suggest PLAC1 as a novel target gene of NCOA3 in ERα-positive MCF-7 breast cancer cells supporting the role of both factors in breast cancer biology." (PMID 24304549, 2013). "In contrast, PLAC1 transactivation was nearly abolished in cells lacking NCOA3, further confirming the important function of NCOA3 for E2/ERα-induced transactivation of PLAC1 in breast cancer cells." (PMID 24304549, 2013). "We detected selective recruitment of NCOA3 but not NCOA1 or NCOA2 to the PLAC1 promoter only in ERα-positive MCF-7 cells but not in ERα-negative SK-BR-3 breast cancer cells." (PMID 24304549, 2013). "However, expressions of candidate PPP genes that changed with NCOA3 activity in breast cancer did not significantly alter in ccRCC." (PMID 34593007, 2021). "In the present study, we examined the involvement of p160/NCOA family members in the regulation of PLAC1 in ERα-positive and -negative breast cancer cells and identified NCOA3 as a selective co-activator of ERα-mediated transactivation of PLAC1 in ERα-positive MCF-7 breast cancer cells." (PMID 24304549, 2013). "Moreover, an in vitro study has shown 17 β-estradiol to upregulate the expression of CYP2B6 exclusively in T-47D but not in MCF-7 breast cancer cells by increasing the recruitment of ER-α and nuclear receptor coactivator 3 (NCoA3) to the 5’ flanking region of the enzyme." (PMID 33809117, 2021). "Therefore, the suppression of NCOA3 that results in inhibition of estrogen-induced degradation of ESR1, but not degradation induced by fulvestrant or GW5638, could have additional clinical effects for ESR1-positive breast cancer." (PMID 19007432, 2008). "In a first experiment, we analyzed expression of NCOA1, NCOA2 and NCOA3 in ERα-positive MCF-7 and ERα-negative SK-BR-3 breast cancer cells that both have been shown to express PLAC1 protein." (PMID 24304549, 2013).
breast carcinoma (continued). "However, the NCOA3-p300-NF-κB complex functions as a mediator of the expression of four antiapoptotic genes in HME1 cells (with low ER levels) and in ER-positive breast cancer cells, suggesting that this regulatory mechanism is not cancer-specific." (PMID 36853387, 2023).
prostate carcinoma (38 papers, 2008 to 2025). A carcinoma that arises from epithelial cells of the prostate gland. "NCOA3 is also linked to prostate cancer cell proliferation and survival and is a key target of the ubiquitin ligase SPOP [mutated in 6–15% of prostate cancer]." (PMID 25896606, 2015). "The plot was thickened with associations between the expression of NCOA1, NCOA3, and MED27, lymph node involvement, and the overexpression of several genes linked to advanced prostate cancer stages." (PMID 40900470, 2025). "Some scholars reported that cell proliferation was inhibited and the cell cycle G1/S phase was arrested by down-regulating the expression of NCOA3 in prostate cancer cells." (PMID 35898549, 2022). "■ NCOA1, NCOA3, MED27, and ESRRA are associated with advanced prostate cancer." (PMID 40900470, 2025). "High NCOA3 protects prostate cancer cells from treatment with another anti-androgen, bicalutamide." (PMID 37435460, 2022). "In SPOP-mutant prostate cancer, several dysregulated SPOP substrates (e.g., NCOA3, TRIM24, BET proteins) have been shown to boost the AR pathway leading ultimately to high levels of AR target genes 3,13,19–26." (PMID 33531470, 2021). "Among them, NCOA3/SRC3 is a co-activator for androgen receptor (AR) and promotes PCa tumorigenesis; DEK acts as a proto-oncogene involved in mRNA processing and DNA replication; ERG is one member of ETS family of transcription factor, and considered as one marker for prostate cancer." (PMID 30237511, 2019). "Targeting NCOA3 via genistein reduces cell proliferation and suppresses the development of prostate cancer in transgenic rat models, although knockout of NCOA1 does not significantly alter prostate cancer initiation and progression." (PMID 37435460, 2022).
breast tumors (22 papers, 2002 to 2025). "Finally, NCOA3 (AIB1) is amplified in 11% of breast tumors and is associated with a worse prognosis in ER+, but also ER− tumors; its tumorigenic potential may therefore result from a role as coactivator of other transcription factors, such as E2F1." (PMID 27729460, 2017). "PTK6 maps to a chromosomal region (20q13.3) that is frequently amplified in breast tumors and amplicons spanning this region variably contain other suspected oncogenes, such as TDE1, NCoA3, BCAS4, and ZNF217." (PMID 20668531, 2010).
ovarian carcinoma (20 papers, 2003 to 2023). A malignant neoplasm originating from the surface ovarian epithelium. "Recent evidence has revealed that amplification of the NCOA3 gene is highly associated with primary chemoresistance in ovarian cancers, suggesting that SRC-3 is most likely a driver in chemoresistance." (PMID 33589584, 2021). "NCOA3 gene is amplified in ovarian cancer and elevated NCOA3 expression has been reported in 64% of high-grade ovarian cancers, and its levels are associated with tumour progression." (PMID 29545931, 2018). "Low expression of NCOA3/SRC3 protein in ovarian cancer tissues, as compared with high expression, was associated with better prognosis in patients undergoing carboplatin monotherapy (P < 0.001), but not in those undergoing combined carboplatin and paclitaxel therapy (P > 0.05)." (PMID 30791431, 2019). "In addition, immunohistochemistry in ovarian carcinoma tissue samples revealed that strong NCOA3 expression was associated with higher stages (i.e., stages III and IV) and worse patient outcomes (HR = 1.349, P = 0.015 in a multivariate analysis for OS)." (PMID 30791431, 2019). "Patients with shorter (≤28) CAG repeats in the NCOA3 gene were also shown to have a higher risk of disease progression (HR = 1.28, 95% CI = 1.01–1.66, P = 0.05 in a multivariate analysis for overall survival) after initial cytoreductive surgery for ovarian cancer." (PMID 30791431, 2019). "In BG-1 ovarian cancer cells, NCOA3 was found to be amplified, whereas SRC-1 and TIF2 (SRC-2) were not." (PMID 30791431, 2019). "NCOA3 was also found to be a marker for platinum resistance in ovarian cancer." (PMID 35252174, 2022). "While SRC-3 (also called as AIB1, or RAC3/ACTR/TRAM-1/NCOA3) was originally identified by its frequent amplification in breast and ovarian cancers and subsequently demonstrated it is homologous to SRC-1 and SRC-2." (PMID 35873031, 2022). "Even though we could not validate if NAC1 immnoprecipitated NCOA3 in several ovarian cancer cell lines due to the quality of anti-NCOA3 antibody which could not detect endogenous NCOA3 expression, it is highly possible that NAC1 formed protein complex with CARM1 and NCOA3." (PMID 29983869, 2018).
colorectal cancer (18 papers, 2010 to 2025). A primary or metastatic malignant neoplasm that affects the colon or rectum. "Though NCOA3 mutations were a favorable prognostic factor in the combined cohort, NCOA3 mutations were predominant in colorectal cancer patients, followed by melanoma and bladder cancer patients." (PMID 35798829, 2022). "We subsequently evaluated the relationship between NCOA3 mutation and survival in these cohorts and found that NCOA3 mutation was associated with improved survival only in colorectal cancer, though this bordered on the threshold for statistical significance." (PMID 35798829, 2022). "MAD2L2 inhibits the growth of colorectal cancer by degrading nuclear receptor coactivator 3; it is a poor prognostic factor for colon cancer." (PMID 36012568, 2022). "The oncogene Ncoa3 (Nuclear receptor coactivator 3) is over-expressed in numerous cancer types such as breast, prostate, ovarian, gastric, pancreatic and colorectal cancers." (PMID 20102610, 2010). "In addition to TET1 and RNF43, our study also identified an association between NCOA3, CREBBP, and NOTCH3 mutations and improved survival in colorectal cancer patients." (PMID 35798829, 2022). "However, NOTCH3 mutation was only associated with improved survival in the colorectal cancer group, though unlike NCOA3, this relationship was highly significant." (PMID 35798829, 2022). "However, little is known about how NCOA3 is regulated in colorectal cancer (CRC)." (PMID 29360267, 2018). "Nuclear receptor coactivator 3 (NCOA3) is a transcriptional coactivator that has elevated expression in multiple tumor types, including colorectal cancer (CRC)." (PMID 29360267, 2018).
hepatocellular carcinoma (17 papers, 2011 to 2025). A malignant tumor that arises from hepatocytes. "Previous research has shown that NCOA3 is associated with the biological functions of several types of human diseases, such as hepatocellular carcinoma and chronic kidney disease; however, a correlation between NCOA3 and UC has not been detected." (PMID 36658474, 2023). "However, some studies have reported that amplification of NCOA3 appears to be independently associated with poor prognosis in patients with hepatocellular carcinoma, and moderate or high expression of NCOA3 is associated with poor disease‐specific survival in patients with prostate disease." (PMID 29360267, 2018). "Dual‐specificity tyrosine (Y) phosphorylation‐regulated kinase (DYRK) 3 reprograms purine synthesis by blocking NCOA3/ATF4 TF complex in hepatocellular carcinoma." (PMID 35092699, 2022). "Via regulating the telomerase reverse transcriptase (TERT) signaling, NCOA3 promoted cell viability and colony formation in hepatocellular carcinoma cells, and high expression of NCOA3 had worse prognosis." (PMID 34593007, 2021).
lung carcinoma (16 papers, 2011 to 2023). "NCOA3 may be an oncogene for lung cancer due to its role in promoting lung cancer cell invasion." (PMID 29484121, 2018).